EPOR (erythropoietin receptor)
Diseases named in the same sentence as EPOR in open-access papers (continued):
Sharing a sentence is not in itself a finding about the gene and the disease.
cancer (continued). "Clinical studies exploring prognostic significance of EPO and EPOR expression in cancer patients." (PMID 25426117, 2014). "The presence of functional EPOR was demonstrated in cancer stem cells." (PMID 25426117, 2014). "In conclusion, we postulate that some support for the embryonic rest hypothesis of cancer development is lent by described by us herein presence of EpoR in both VSELs and germline-derived cell lines." (PMID 24982693, 2014). "For instance, miR-125b downregulates EPO and EPOR expression in breast MCF7 cancer cell lines." (PMID 25324845, 2014). "EPO and its receptor, EPOR, are expressed in many cancers, including RCC." (PMID 23305401, 2013). "Epo and EpoR expression has been reported in many tumors including RCC, but the function of Epo/EpoR pathway is largely unknown in cancer cells." (PMID 23028796, 2012). "The authors proposed that there may be an Epo-independent, EpoR-mediated pathway in the growth of some human cancers." (PMID 23028796, 2012). "Epo/EpoR pathway may play more important roles in RCC than in other cancers, because of the specific site of RCC which closely adjoins the Epo secreting tissue." (PMID 23028796, 2012). "The presence of EpoR in cancer tissues, if functional, could have unintended consequences in patients who use rhEpo for radiation- and chemotherapy-associated anemia." (PMID 22188703, 2011). "Thus, the development of novel reagents and techniques to accurately quantify EPOR expression in primary human tumors is required as a tool to further characterize EPO biology in cancer." (PMID 17579721, 2007). "Although local erythropoietin blockade in tumors may represent one approach to overcome this problem, selective inhibition of EPOR function to specifically target cancer cells may constitute an alternative future strategy." (PMID 17579721, 2007). "We hypothesized that EPOR also controls the mitochondrial metabolism in cancer cells." (PMID 36052260, 2022). "Furthermore, some cancer cells may exhibit constitutive activation of EPOR pathways, suggesting that observed effects of signal transduction through the EPOR in these cells are EPO-independent." (PMID 35694408, 2022). "Moreover, EPOR expression per se may also be a clinical predictor of cancer cell responsiveness to drugs and radiation, which depends on mitochondrial metabolism." (PMID 36052260, 2022). "This study resolves the controversy of whether EPOR is highly or lowly expressed in cancer." (PMID 35359375, 2022). "The expression and prognosis of EPOR in cancer remain unclear." (PMID 35359375, 2022). "In addition, human and experimental studies have shown the co-expression of EPO/EPO receptor in various human malignancies and also demonstrated that the EPO/EPOR signaling plays a significant role in cancer cell proliferation, migration, invasiveness, and in the inhibition of apoptosis." (PMID 24155958, 2013). "Therefore, further studies are necessary to evaluate the role of rhEpo/EpoR in human cancers." (PMID 22188703, 2011). "Consequently, the adverse outcome of Epohigh patients could be related to the higher odds of reaching certain Epo thresholds, which are necessary for the mobilization or recruitment of EpoR-positive cancer (stem) cells, notwithstanding sol-EpoR." (PMID 21829709, 2011). "Pediatric cancers often have developmental origins, making the role of EPO/EPOR even more intriguing." (PMID 38542288, 2024). "The activation of the main EPO/EPOR downstream pathways (JAK2-STAT5, PI3K-AKT, MAPK/ERK) has been demonstrated in cancer cells." (PMID 35694408, 2022). "Similar observations were made for EPOR and KLF1; both genes showed significant co-expression with GATA2 and positive GATA2 binding observed for multiple cancer cell lines in ChIP-seq experiments." (PMID 35087776, 2021). "It is reported that activated EPOR signals through JAK2 and downstream STAT5, PI3K/AKT or RAS/RAF/ERK to promote pro-proliferative or anti-apoptotic cancer cell growth." (PMID 29137269, 2017).
cancer (continued). "EPOR has been identified in a number of cancer cells, and therapy with ESAs has a known effect of negatively impacting the survival of patients with malignancy." (PMID 39155928, 2024). "EPOR cytokine receptor occurs in diverse types of cells, mainly erythropoietic progenitors and several types of non-hematopoietic tissues as well as cancer cells." (PMID 37239828, 2023). "Moreover, the effect of EPOR, as the receptor of EPO, on the prognosis of cancer patients has been discussed." (PMID 35359375, 2022). "EPOR is expressed in non-hematopoietic tissues including cancer cells, suggesting that it plays a role beyond erythropoiesis in malignant tissues." (PMID 36052260, 2022). "Very high methylation was also observed in A549 cell line (86%) and in EPOR negative cancer cell line 769P (73%)." (PMID 30606107, 2019). "The majority of our selected cancer cell lines, with the exception of A2780 cell line, showed negative correlation between the monitored methylation of EPOR CpG sites and its transcription." (PMID 30606107, 2019). "In this regard, we have examined several cancer cell lines (DLD1, HepG2, P39, T98G, PC-3, G361, SCH), of which expression levels of Epo and EpoR are already known, to investigate whether rhEpo triggered and EMP9 inhibited tyrosine phosphorylation of STAT5." (PMID 25874769, 2015). "While no or reduced EPOR expression was identified as prognostic factor for increased overall survival and in contrast, also to increased cancer recurrence rate." (PMID 25426117, 2014). "Here we show that with A82, no EpoR protein was detectable in normal human and matching cancer tissues from breast, lung, colon, ovary and skin with little/no EpoR in MCF-7 and most other breast and lung tumor cell lines." (PMID 23861852, 2013). "To elucidate the functional role of EPO/EpoR signaling in cell proliferation and/or cell survival, we analyzed the effects of EPO stimulation on genes involved in the cell cycle, such as PCNA and CyclinD1, as previously observed in other cancer cell lines." (PMID 23052842, 2013). "In addition, high levels of EPO and EPO receptor (EPOR) were found in various cancer cell types and the EPO/EPOR system was known to induce proliferation, angiogenesis and even inhibit apoptosis." (PMID 23825635, 2013). "Erythropoietin (EPO) and its cell surface receptor (EPOR) are essential for erythropoiesis; can modulate non-erythroid target tissues; and have been reported to affect the progression of certain cancers." (PMID 22253704, 2012). "The testing of the available mathematical model in an appropriate experimental system and its validation in clinical material are further steps towards clarifying the role of the Epo/EpoR system in PDAC and towards optimization of rhEpo-based treatments of anemic cancer patients." (PMID 21829709, 2011). "As such, the impact of EPOR expression on the prognosis of cancer patients cannot be determined, and whether it can be a valid prognostic marker for cancer remains to be explored, as well as the lack of studies on EPOR in pan-cancer." (PMID 35359375, 2022). "Furthermore, in some studies using a sensitive A82 anti-EPOR antibody no EPOR was detected or it was detected only in low levels in many different cancer cell lines." (PMID 30606107, 2019). "Bearing in mind that EPOR-expressing erythroid cells are the main target cells for EPO, these findings are in accordance with previously published data implying that adequate inhibition of EPO function in cancer patients might improve the therapeutic efficacy of antiangiogenic therapy." (PMID 35694408, 2022). "In contrast, some cancer cell lines have been reported to be non-responsive to EPO, although they express EPOR transcripts, but not functional EPOR." (PMID 36052260, 2022).
infection (10 papers, 2010 to 2026). The state of being infected such as from the introduction of a foreign agent such as serum, vaccine, antigenic substance or organism. "Myeloid-specific EPOR-deficient mice exhibited an impaired inflammatory resolution and exogenous EPO enhanced this resolution in self-limited infections." (PMID 33927725, 2021). "We first detected the temporal expression of EPO and EPOR in a self-limited infection model induced by intraperitoneal administration of E. coli (105 c.f.u. per mouse)." (PMID 33927725, 2021). "EPOR suppression at less than half of the pre-infection levels was reflected in the number of reticulocytes in wild type mice." (PMID 30586912, 2018). "While erythropoietin receptor (EpoR) signaling is associated with the strict erythroid tropism of B19V, it is not required for infection in trophoblasts." (PMID 41706746, 2026). "Considering the central role of bacterial clearance in infection resolution and the restricted localization of EPOR in macrophages, we evaluated whether EPO influences macrophage containment of E. coli in vitro." (PMID 33927725, 2021). "Strong support for this hypothesis came from studies demonstrating that the IL-3-dependent cell line BaF3 could be converted to factor-independence by SFFV-P infection if and only if a construct driving exogenous expression of the EpoR was introduced." (PMID 21994618, 2010). "Furthermore, myeloid EPOR deficiency resulted in a prolonged Ri (approximately 20 hrs in the EPOR-cKO mice and approximately 16 hrs in the control mice), indicating the important role of macrophage EPO signaling in promoting infection resolution." (PMID 33927725, 2021). "Interestingly, the mRNA expression levels of EPOR was dramatically suppressed in the bone marrow at early stage of infection, independent of the severity of anemia, EPO expression, and parasitemia levels in both α-TTP knockout and wild type mice." (PMID 30586912, 2018). "In the bone marrow, the mRNA expression of erythroid differentiation genes (α-globin, β-globin, ALAS2) were inhibited by 50%, but mRNA levels of erythroid receptor (c-kit, EpoR) and transcription factors (GATA1, GATA2, FOG1) were not affected by the infection." (PMID 23533629, 2013). "However, administration of rhEPO to the EPOR-cKO mice following infection did not result in a significant decrease in the Ri, indicating the central role of macrophage EPO signaling to infection resolution." (PMID 33927725, 2021). "The Epo-dependent erythroleukemia cell line HCD-57 can grow in the absence of Epo after infection with either SFFV-P or SFFV-A, but only SFFV-P can confer factor-independence to BaF3-EpoR cells, an IL-3 dependent hematopoietic cell line that has been engineered to express the Epo receptor (EpoR)." (PMID 21994618, 2010).
adenocarcinoma (3 papers, 2007 to 2022). A common cancer characterized by the presence of malignant glandular cells. "In this study, we examined the expression of EpoR and Akt in adenocarcinoma cells as well as EpoR, VEGF, Flt-1, and CD31 expression in xenografts." (PMID 27543111, 2016).
kidney disease (3 papers, 2015 to 2025). "The current data from the CREDENCE trial provides new evidence on the association of anti-EPOR antibodies with CV and kidney events in a population with T2D and more severe kidney disease." (PMID 38344715, 2024). "Autoantibodies to erythropoietin receptor (anti-EPOR antibodies) have been identified in patients with various kidney diseases." (PMID 38344715, 2024). "Anti-EPOR antibodies remained significant after adjusting for kidney disease parameters alone (eGFR and log-transformed UACR - model 2), or for both kidney and CV parameters (eGFR, log-transformed UACR, history of CV disease and systolic blood pressure - model 3)." (PMID 38344715, 2024). "Previously, a nested case-control study of a randomized controlled trial reported that anti-EPOR antibodies improved the prediction of kidney disease progression independent of traditional risk factors in patients with T2D at high CV risk." (PMID 38344715, 2024).
blood cancers (2 papers, 2020 to 2022). "Ongoing structure–function studies of the EPOR and its essential partner, tyrosine kinase JAK2, suggest that it may be possible to generate new “designer” drugs that control selected subsets of cytokine receptor activities for therapeutic manipulation of hematopoiesis and treatment of blood cancers." (PMID 32983414, 2020).
hematopoietic cancers (2 papers, 2012 to 2016). "JAK2V617F associated hematopoietic cancers are much better understood in the context of JAK2V617F linkage with receptors such as EpoR for both activation and specific function in the nucleus." (PMID 28077919, 2016).
neurological disease (2 papers, 2009 to 2012). "Many experimental studies have shown that both Epo and its specific receptor (erythropoietin receptor, EpoR) expressing in the CNS, provide remarkable neuroprotection in many neurological diseases." (PMID 23211059, 2012).
genetic disorders (1 paper, 2021). "Primary genetic disorders in the erythropoietin receptor gene (EPOR) are ECYT1 and ECYT 2–8 are secondary disorders, with genetic lesions leading to secondary erythrocytosis." (PMID 34440325, 2021).
EPOR also shares sentences with these, for which no sentence is quoted: renal failure (5 papers); injury (4); end-stage renal disease (3); head and neck tumours (3); hematologic disorder (3); mesothelioma (3); metabolic syndrome (3); monoclonal gammopathy of undetermined significance (3); acute lung injury (2); brain tumors (2); gastric cancer (2); immune dysfunction (2); lung squamous cell carcinoma (2); pulmonary fibrosis (2); retinal degeneration (2); squamous cell carcinoma (2); Type 2 Diabetes (2); uterine cancer (2); Alport syndrome (1); amyotrophic lateral sclerosis (1); angiomyolipoma (1); Barrett's metaplasia (1); benign prostatic hypertrophy (1); benign tumors (1); bladder urothelial carcinoma (1); carcinoid tumor (1); carcinoma of head and neck (1); cardiovascular disease (1); cerebral infarction (1); cerebral oedema (1).
A further 58 diseases each share a sentence with EPOR in 1 paper.